FOXM1 (forkhead box M1)
Diseases named in the same sentence as FOXM1 in open-access papers (continued):
Sharing a sentence is not in itself a finding about the gene and the disease.
breast cancer (continued). "While FOXM1 plays a critical role in these processes in breast cancer cells and tumors, we do not know that the effect of the NB compounds is specific to only FOXM1 inhibition in these cells." (PMID 32961773, 2020). "FOXM1 can also target XIAP and Survivin to modulate breast cancer survival and chemoresistance." (PMID 33371405, 2020). "Although FOXM1 and FOXO3A have been suggested to cooperate in the regulation of ERα gene transcription, FOXO3A has been reported to inhibit ERα activity and suppresses the outgrowth of ERα+ breast cancer." (PMID 32967092, 2020). "Having observed the effect of the FOXM1 inhibitory compounds on TNBC cell motility and invasion, we next investigated their effect on expression of important EMT-related genes known to be involved in breast cancer metastasis." (PMID 32961773, 2020). "FOXM1 degradation can be regulated by both E3 ubiquitin ligase, such as APC/C-Cdh1, and deubiquitinases, such as USP5, USP21, and OTUB1 in glioblastoma and breast cancers." (PMID 33142744, 2020). "Analysis of the METABRIC dataset showed that increased FOXM1 expression correlates with poorer survival in PIK3CA mutant breast cancer patients, and that breast cancer-specific survival rate is decreased in ER+ breast cancer patients with FOXM1 copy number gain." (PMID 32976773, 2020). "Consistently, FOXM1 is also overexpressed in clinical breast cancer sample and significantly higher in triple‐negative breast cancer." (PMID 31359594, 2019). "To further investigate the hypothesis that FOXM1 is a downstream signaling target of PML in breast cancer, we studied the effect of PMIV induction on FOXM1 protein and mRNA expression levels over a 48‐h time course." (PMID 30927552, 2019). "Although 1222 target genes of miR-10b-5p were predicted and 48 significantly negatively correlated genes were obtained, only 5 overlapped genes, BIRC5, E2F2, KIF2C, FOXM1, and MCM5, were considered as potential key targets of miR-10b-5p in breast cancer for further analysis." (PMID 31579605, 2019). "Moreover, in a TCGA dataset of breast cancer patients, we found an enrichment of VEGFA mRNA in HMGA1 or FOXM1 overexpressing patients." (PMID 31311575, 2019). "Thus, we stratified breast cancer samples according to their relative expression levels of HMGA1 and FOXM1, obtaining a significant enrichment in VEGFA expression in patients in which the HMGA1/FOXM1 axis is activated." (PMID 31311575, 2019). "For example, we showed previously that relative expression of proliferation-related and immune response-related genes, i.e., UBE2C, TOP2A, RRM2, FOXM1, MK167, and BTN3A2, provided a prediction value of adjuvant chemotherapy benefit for patients with ER+/HER2− early breast cancer." (PMID 31779659, 2019). "Interestingly, the low survival probability of patients that co-express HMGA1, FOXM1 and VEGFA at high levels has also been observed both in breast cancer datasets and in a subset of TNBC patients." (PMID 31311575, 2019). "A considerable amount of data sustains the involvement of FOXM1 in several features of breast cancer progression, such as the EMT, the migration and invasion abilities of tumor cells, in which FOXM1 controls the transcription of several metalloproteinases and the EMT inducer SNAI2." (PMID 31311575, 2019).
breast cancer (continued). "Indeed, in breast cancer patients a profound molecular relation between HMGA1, FOXM1 and VEGFA has been further highlighted by TCGA analysis, which confirmed a strong enrichment of VEGFA in patients that overexpressed HMGA1 and FOXM1." (PMID 31311575, 2019). "Nevertheless, viewpoints on the role of FoxM1 in breast cancer were mostly from basic studies, and lacking support from clinical data." (PMID 29416660, 2018). "The effects of treatment with Sepin-1 that are similar on the four breast cancer cell lines include non-activation of caspases 3 and 7 and downregulation of cell cycle-driving proteins, such as Raf, FoxM1, Plk1, Cdk1, Aurora A, Lamin B1, and pericentrin." (PMID 29780443, 2018). "The significance of this regulation of Exo1 by FOXM1 in DDR is highlighted by the revelation that FOXM1 modulates the sensitivity to the DNA-damaging agents, cisplatin and doxorubicin, through regulating EXO1 in ovarian and breast cancer, respectively." (PMID 29180117, 2018). "As far as we know, FoxM1 could lead to CSC phenotype in several cancers including ovarian cancer, breast cancer, colon cancer, pancreatic cancer and glioblastoma." (PMID 30416986, 2018). "Importantly, FoxM1 overexpression is found to be an independent prognostic marker in multivariate analysis in advanced stage (Stage III and IV) breast cancer (p = 0.0298)." (PMID 29707121, 2018). "In stark contrast, expression of the remaining 5 mitotic kinesins that are not regulated by MMB and FOXM1 was not correlated with survival and their expression did not strongly differer in specific breast cancer subtypes." (PMID 28061449, 2017). "Knockdown of FoxM1 rescued EMT and invasiveness of GDF15-overexpressing breast cancer cells." (PMID 29212236, 2017). "This indicates that FOXM1 targets in MCF-7 cell lines reflect estrogen receptor activity in breast tumor samples, implying that ERα serves as the major factor that mediates FOXM1 genomic binding in ER+ breast cancer." (PMID 29100329, 2017). "To further elucidate the molecular mechanism through which GDF15 enhances breast cancer cell invasion, we measured expression levels of matrix metalloproteinases (MMP) MMP2 and MMP9, which are transcriptional targets of FoxM1 and mediators of cancer cell invasion." (PMID 29212236, 2017). "In particular, in breast cancer the transcription factor Forkhead box protein M1 (FoxM1) is known to induce EMT via SNAI2 (SLUG) promoter stimulation, while in pancreatic cancer, FoxM1 upregulates ZEB1, ZEB2, SNAI2 and vimentin." (PMID 28792442, 2017). "We further demonstrated that the AURKA and FOXM1 inhibitors can function synergistically to inhibit AURKA activity and disrupt the positive feedback loop to more effectively limit the tumorigenicity of breast cancer cells." (PMID 28114286, 2017). "By systematically comparing the binding sites and target genes of FOXM1, we find that even though MCF-7 and MDA-MB-231 are both breast cancer cell lines, FOXM1 binding events are substantially different between these two cell lines compared to non-breast cell lines." (PMID 29100329, 2017). "This includes how FOXM1 impacts on different subtypes of breast cancer, that is, luminal/estrogen receptor positive (ER+), expressing human epidermal growth factor receptor 2 (HER2), basal-like breast cancer (BBC), and triple negative breast cancer (TNBC)." (PMID 26942015, 2016). "FoxM1 downregulates ROS levels by stimulating expression of ROS scavenger genes, such as MnSOD, catalase and PRDX3; the Nrf2-Prx I axis is important in human lung-cancer, prostate-cancer, colon-cancer, and breast-cancer development." (PMID 27517622, 2016). "Their work suggested that FOXM1 may in fact be a downstream target and marker of HER2 overexpression in breast cancer." (PMID 26942015, 2016). "The baseline expression of FOXM1 was determined in various human breast cancer cell lines and non-tumorigenic human breast cells (MCF10A) by Western blot analysis." (PMID 26918606, 2016).
breast cancer (continued). "At present, however, there is no clear biomarker developed to assess sensitivity of breast cancer to FOXM1 inhibition." (PMID 26942015, 2016). "Developing clinically applicable therapies that specifically inhibit FOXM1 activity is a logical next step in biomarker-driven approaches against breast cancer but will not be without its challenges due to the unique properties of this transcription factor." (PMID 26942015, 2016). "FOXM1 induces STMN1 expression in B-cell lymphoma, breast cancer and gastric cancer." (PMID 26973435, 2016). "In addition, these data also underscore the value of FOXM1 and KIF20A as biomarkers for the prediction of breast cancer chemotherapy sensitivity and patient survival." (PMID 25961928, 2016). "To explore the potential regulation of FOXM1 by OTUB1 in response to genotoxic agents, we investigated the expression of OTUB1 and FOXM1 in the epirubicin-sensitive MCF-7 and epirubicin-resistant MCF-7EpiR breast carcinoma cell lines following epirubicin treatment." (PMID 26148240, 2016). "Our data indicate that FoxM1 upregulated the levels of PDGF-A and phospho-AKT in breast cancer cells; therefore, we investigated whether the activation of the AKT pathway by FoxM1 depends on PDGF-A." (PMID 25869208, 2015). "The regulatory feedback between FoxM1 and the PDGF/AKT pathway revealed in our study may represent a critical mechanism for the proliferation and tumorigenesis of human breast cancer." (PMID 25869208, 2015). "Furthermore, expression of FoxM1 significantly correlated with the expression of PDGF-A and the activated AKT signaling pathway in human breast cancer specimens." (PMID 25869208, 2015). "We analyzed the significance of the FoxM1/PDGF-A/AKT axis in a panel of 67 human breast cancer specimens and 10 adjacent non-tumor tissues." (PMID 25869208, 2015). "Owing to the great importance of the FoxM1/PDGF-A/AKT axis in human cancers, our findings strongly suggest that targeting FoxM1 may be an alternative therapeutic strategy for breast cancer." (PMID 25869208, 2015). "Notably, the expression levels of FoxM1 and MELK demonstrate a striking correlation across all breast cancer samples and subtypes examined." (PMID 24844244, 2014). "In addition, FOXM1 has been shown to be one of the ERK effectors in human hepatocellular carcinoma and breast cancer." (PMID 21858223, 2011). "In normal breast tissue FOXM1 expression was often absent or weaker in the nucleus compared with breast carcinomas." (PMID 18254960, 2008). "USP39 and FOXM1 form a negative feedback loop that co-controls breast cancer cell proliferation." (PMID 40990019, 2025). "Intriguingly, FOXM1 overexpression was found to be highest in Triple-negative breast cancer (TNBC), the most aggressive BC with the worst prognosis." (PMID 39762471, 2025). "In breast cancer (BC), the transcription of ITGB1 is activated by CDC42, FOXM1, HIF1α, and EZH2 to support the ability of BC cells to invade and spread." (PMID 38279122, 2024). "FoxM1 could target XIAP and survivin to promote cell growth and chemoresistance of breast cancer." (PMID 36860922, 2023). "Similarly, breast cancer cells with inhibited OGT expression show a reduction in phosphorylation of ERK, which leads to a reduction in expression of pro-proliferation protein Forkhead Box M1 (FoxM1)." (PMID 37838167, 2023). "Similarly to the patterns of expression of mitotic kinases in breast cancers that do not fall under traditional classification (or that failed to classify) FOXM1, E2F1, E2F2, E2F3, and c-Myc are overexpressed in that subtype." (PMID 36494865, 2022). "Moreover, it was demonstrated that FOXM1 upregulation inhibits tumor growth by silencing FBXL19-AS1 and that the FBXL19-AS1/miR-8765p/FOXM1 axis might regulate breast cancer cell proliferation." (PMID 36649030, 2022).
breast cancer (continued). "We validated the correlation between YTHDF1 and FOXM1 expression in breast cancer patients from TCGA by estimating the Pearson's correlation coefficient R. The result indicated a positive correlation (r = 0.31, P = 2.96e–29) between YTHDF1 and FOXM1 expression." (PMID 35197112, 2022). "Furthermore, these data also point to a role for HER2 and FOXM1 in resistance to ERα inhibition in ER+ breast cancer cells without HER2 amplification or in the absence of activating HER2 mutations." (PMID 33920089, 2021). "In addition, we confirmed that the expression levels of the three genes, ASPM, CDCA8 and KIF2C, were significantly reduced following the knockdown or silencing of FOXM1 based on both microarray data in BT-20 breast cancer cells (GSE2222) and RNA-seq data in MCF-7 breast cancer cells (GSE58626)." (PMID 33667222, 2021). "In addition, HIF1α also plays key roles in promoting CSC phenotypes through ITGA6 forkhead box protein M1 (FOXM1), miR-215, and signal transducer and activator of transcription 3 (STAT3) activation in breast cancer, pancreatic cancer, colon cancer, and glioma, respectively." (PMID 34482364, 2021). "This suggests that there is a switch from ERα-dependent to HER2-dependent and ERα-independent expression of FOXM1 when patients progress under endocrine treatment, even in ER+ breast cancer cells that do not have HER2 amplification or activating HER2 mutations." (PMID 33920089, 2021). "Interestingly, in another human mammary epithelial cell line (HMEC) (GSE62425), the binding of FOXM1 to CDCA8 was absent, suggesting the emerging binding of FOXM1 to certain genes during the formation of breast cancer." (PMID 33667222, 2021). "In summary, our findings demonstrate that DNMT1/FOXO3a/FOXM1/SOX2 signaling promotes BCSC properties, which might contribute to tumor initiation and progression in breast cancer, and that targeting this signaling is a potential therapeutic strategy for breast cancer." (PMID 31296961, 2020). "Importantly, we observed a significant inverse correlation between FOXO3a and FOXM1/SOX2/DNMT1 expression levels, and a significant positive correlation between FOXM1, SOX2, and DNMT1 in the breast cancer tissue set, which was consistent with our finding in vitro and in animal model." (PMID 31296961, 2020). "Therefore, one of the mechanisms by which FOXO3 protein could inhibit DDR in breast cancer, would be the inhibition of the transcription of DDR-genes induced by FOXM1." (PMID 32332845, 2020). "As FOXM1 can directly bind to target sites by recognizing the canonical binding motif in the MCF-7 cell line, FOXM1 could be a key transcription factor in regulating various pathways in estrogen receptor (ER)-positive breast cancer." (PMID 32858881, 2020). "However, the clinical relevance of FoxM1 expression has not been investigated in breast cancer in Saudi Arabia, a country with a particularly more aggressive breast cancer and an unusually young age of onset." (PMID 29707121, 2018). "Additionally, it is worth mentioning that our data pointed out a positive correlation between the expression of both genes, as well as of FOXM1 protein and UBE2C gene expression, and also demonstrated that FOXM1 binds onto UBE2C promoter in a breast cancer cell line." (PMID 29596365, 2018). "Likewise, a statistically significant downregulation of BIRC5 transcription as well as FOXM1 expression was obtained in breast cancer patients irrespective of their subclass, as well as in TNBC patients." (PMID 28187446, 2017). "Recently, analysis of The Cancer Genome Atlas (TCGA) breast cancer database also identified FOXM1 as the key transcriptional driver in the differentially expressed gene signature of TNBC, demonstrating the significance of FOXM1 as a driver of proliferation and disease progression." (PMID 26918606, 2016).
breast cancer (continued). "Our analyses suggest that the deregulation of FOXM1 and AURKB pathways may contribute to the progression from hormone-dependent to hormone-independent growth of breast cancer since our results show that the activity of both pathways is higher in ER-negative, PGR-negative breast cancer." (PMID 25213199, 2014). "However, the potential roles of FOXO3a/FOXM1 in casticin-induced apoptosis in breast cancer cells had not yet been investigated." (PMID 24765206, 2014). "Moreover, our functional work clearly shows that rendering the FOXM1 pathway inactive by RNAi knockdown or by use of the p19ARF 26-44 peptide, a selective FOXM1 peptide inhibitor called ARF, was highly effective in restoring endocrine sensitivity and suppressing breast cancer aggressiveness." (PMID 25213081, 2014). "Additionally, in current research, FOXM1 amplification was reported to confer primary resistance of gefitinib in non-small cell lung cancer (NSCLC) and acquired paclitaxel resistance in breast cancer, showing implications in resistance to chemotherapy strongly." (PMID 24004449, 2013). "Indeed, knockdown of FoxM1 in breast cancer cells also led to an increase in DNA damage, but did not result in the downregulation of those potential FoxM1 targets, BRCA2, and XRCC1, neither at protein nor mRNA level." (PMID 23467617, 2013). "This inhibitory effect on FOXM1 has not been analysed for human breast cancer so far." (PMID 18254960, 2008). "Moreover, there were higher observed co-expression scores for FOXM1/E2F1, FOXA1/GRHL2, FOXA1/GATA3, suggesting that absence of FOXA1 might contribute to doxorubicin resistance in breast cancer cells through collaboration with the down-regulated GRHL2 and/or GATA3." (PMID 34395436, 2021). "Overall, our findings indicate that these new FOXM1 targeting compounds may have therapeutic potential in treating TNBC with the aim of reducing tumor progression and metastatic outgrowth, and hopefully providing clinical benefit ultimately to patients with this aggressive type of breast cancer." (PMID 32961773, 2020). "However, in our study we could not detect a significant correlation between FOXM1 expression and oestrogen or progesterone receptor status in human breast cancer." (PMID 18254960, 2008). "Both FOXM1 and AURKB were significantly upregulated in brain metastasis samples compared to primary breast cancer samples and non-neoplastic samples." (PMID 24489661, 2014). "In brief, we demonstrated that YTHDF1 binds to the m6A-modified FOXM1 gene at the coding sequence (CDS) region and plays its role as an oncogenic gene by promoting FOXM1 translation rather than transcription, exacerbating the progression of breast cancer." (PMID 35197112, 2022). "Moreover, using a dataset of breast cancer patients we show that the co-expression of HMGA1, FOXM1 and VEGFA is a negative prognostic factor of distant metastasis-free survival and relapse-free survival." (PMID 31311575, 2019).